PMS2 (PMS1 homolog 2, mismatch repair system component)
Diseases named in the same sentence as PMS2 in open-access papers (continued):
Sharing a sentence is not in itself a finding about the gene and the disease.
tumor (522 papers, 2001 to 2026). "Integrating germline genetic data, clinical phenotypes, tumor characteristics, and bioinformatics analyses, we provide relevant evidence suggesting that this novel PMS2 variant is linked to LS." (PMID 40723192, 2025). "Collectively, these data suggested that PMS2 deficiency increased the leakage of nuclear DNA into the cytoplasm, thereby enhancing anti‐tumor immune responses." (PMID 40344511, 2025). "There were no EBV-positive cases, while five cases showed complete loss of MLH1 and PMS2 expressions in all tumor components." (PMID 39488822, 2025). "In summary, the analysis of distinct MLH1/PMS2-expressing tumor regions from a patient with a novel de novo BRCA2 variant provided valuable insights into the evolution of OC." (PMID 40076915, 2025). "Despite substantial in silico and tumor characterization evidence, a limitation of our study is the lack of experimental in vitro validation of the functional role of the PMS2 Gly62Arg variant." (PMID 40723192, 2025). "The approach varied, but typically, if a tumor showed MLH1/PMS2 deficiency and either BRAF positivity or hypermethylation, it was considered likely sporadic, and germline testing was discouraged or pursued only if clinical suspicion remained high." (PMID 40426889, 2025). "Based on our patients’ personal and family history, tumor pathology, and in silico protein structure analysis, the new PMS2 gene variant described in this paper is likely associated with hereditary LS." (PMID 40723192, 2025). "Spatial proteomic analysis of MLH1/PMS2-proficient and -deficient tumor tissues revealed distinct expression profiles between the two areas, which also differed significantly from normal tissue." (PMID 40076915, 2025). "Tumor molecular characterization and bioinformatics analyses indicate that this variant negatively affects PMS2 structural stability and functionality within the MMR system." (PMID 40723192, 2025). "These genetic variants were all confirmed in the tumor area deficient in MLH1/PMS2 protein expression (A2), which confirmed a shared tumor origin; however, this region exhibited a significantly higher tumor burden, indicating its further molecular evolution." (PMID 40076915, 2025). "Specifically, collagen type I α-chains were upregulated over 29-fold in the MLH1/PMS2-deficient tumor area." (PMID 40076915, 2025). "Tumor tissue exhibited loss of MLH1/PMS2 protein expression and microsatellite instability-high (MSI-H), with no detectable BRAF mutations or MLH1 promoter methylation." (PMID 41278281, 2025). "Despite the homogeneous tumor presence of BRCA2 LOH, the MLH1/PMS2-deficient region exhibited a higher mutation burden, potentially indicating a distinct tumor evolutionary trajectory." (PMID 40076915, 2025). "One tumor from each cohort had high tumor mutational burden and microsatellite-instability with PMS2 and ARID1A mutation." (PMID 40634688, 2025). "In the dMMR population, co‐occurring MLH1 and PMS2 protein loss across all tumor types was observed most commonly, in 48/70 (68.6%) patients." (PMID 41313676, 2025). "Both dMMR tumors showed impaired immunoreactivity, with one tumor displaying a simultaneous loss of the MLH1/PMS2 heterodimer and the other showing isolated MSH6 loss." (PMID 40415014, 2025).
tumor (continued). "PMS2 loss was significantly associated with female sex (18% vs. 8.4%, p = 0.015), right-sided tumor location (23.5% in right colon, 8.8% in left colon, and 7.2% in rectum; p = 0.003), and poor differentiation (24.8% in G3, 6.7% in G2, and 0% in G1; p < 0.001)." (PMID 40941629, 2025). "The loss of PMS2 appears to occur rather as a secondary event following a neoplasia-inducing variant in pMMR CRC, such as pathogenic APC variants." (PMID 40612339, 2025). "The two dMMR cases showed loss of MLH1 and PMS2 expressions, and prominently high tumor PD-L1 expression." (PMID 38178127, 2024). "These mutations correlate with a tumor mutation load more than five times higher than in tumors with wild-type PMS2, The PMS2 and MTH1/NUDT1 genes are closely located on chromosome 7 (at 7p22.1 and 7p22.3, respectively)." (PMID 38357002, 2024). "There were 133 cases of loss of PMS2 expression and 104 cases of PMS2 expression among dMMR CRCs, and the differences of lymph node metastasis and tumor location were statistically significant (P < 0.05)." (PMID 38967814, 2024). "Our results reveal enriched signaling pathways from tumor samples with germline mutations in the PMS2 gene including upregulation in pathways related to intrinsic and extrinsic prothrombin activation, fibrinolysis, and uPA/uPAR-mediated signaling." (PMID 39139583, 2024). "Immunohistochemical analysis indicating the loss of MLH1/PMS2 co-expression is associated with a lower tumor mutational burden (TMB)." (PMID 38714954, 2024). "The third case harbored an MLH1 VUS (MLH1 c.400A > G p.Lys134Glu in SLS194) identified in an SST tumor showing loss of MLH1/PMS2 and two somatic MLH1 mutations." (PMID 37101184, 2023). "In one case, classified as inadequate for MLH1 and PMS2, the matched resection specimen showed loss of MLH1/PMS2 in the tumour." (PMID 37284845, 2023). "In the recurrent tumor sample, a P mutation of the MLH1 gene was found, accompanied by loss of both MLH1 and PMS2 immunoreactivities in the tumor cells." (PMID 37891325, 2023). "Histopathologic analysis revealed that the primary tumor and liver metastases were mismatch repair-deficient (BRAFV600E mutant and MLH1/PMS2-deficient), also known as a microsatellite instable tumor." (PMID 36685719, 2023). "If a loss of MLH1 and PMS2 is detected by IHC in tumor tissue, the additional presence of a BRAF V600E variant in tumor tissue or of promotor methylation of MLH1 likely indicates a sporadic CRC case." (PMID 36760167, 2023). "Tumor genomic analysis revealed high TMB (>10 mutations/Mb) in an SMN specimen from SMN04 with a PMS2 variant." (PMID 37021926, 2023). "In another case, UXE-004, loss of PMS2 was found in the parental tumor, and the status was unclear due to poor staining in PDXs with later passages." (PMID 37231035, 2023).
tumor (continued). "In line with this, loss of heterozygosity (LOH) of PMS2 in tumor tissue was demonstrated by the INFORM analyses." (PMID 37308967, 2023). "In detail, when immunohistochemical (IHC) loss of MLH1 and PMS2 proteins is observed in a tumor, both MLH1 germline variants and epigenetic silencing should be considered." (PMID 38003003, 2023). "The CRC from the carrier of in cis variants MLH1: c.-[28A > G; 7C > T] was diagnosed at 35 years of age, showed “patchy” loss of MLH1/PMS2 by IHC in both tumour and adjacent normal cells, with mean β of 0.14 in MLH1 promoter." (PMID 37270516, 2023). "The tumour sample in PanSPS_044 (III-1) showed loss of expression for MLH1/PMS2 and was BRAF mutated and MGMT methylated." (PMID 36270769, 2023). "To further elucidate the role of the PMS2 germline variant in tumor development, we initiated IHC and MSI analysis." (PMID 37308967, 2023). "The tumour is sent to the pathology department for next generation sequencing of PMS2, where one somatic hit in PMS2 with a variant allele frequency of 23% is found." (PMID 36895471, 2023). "For example, SLS116 showed solitary loss of MSH6 expression initially and when repeated internally showed loss of MLH1/PMS2 that was related to tumor MLH1 methylation." (PMID 37101184, 2023). "In total, 20 (69%) of 29 neoplasms with the loss of MLH1/PMS2 expression had an attributable epigenetic MLH1 methylation and/or a somatic null MLH1 mutation." (PMID 36230473, 2022). "He had LS with PMS2 germinal mutation and his tumor was MSI with retained expression of the four MMR proteins." (PMID 34545179, 2022). "Three (Cases #3, 12, and 13) of four MSH6-mutant tumors had MSH6 loss only, but both MSH6 and PMS2 losses were also found in one MSH6-mutant tumor (Patient #8)." (PMID 34848827, 2022). "The NF1 mutations usually co-existed with PMS2 mutations, and this group included more men and young patients who had a high tumor mutational burden and lateral lymph node metastasis rate." (PMID 35865459, 2022). "If there is loss of MLH1 or MLH1/PMS2 expression, somatic tumor mutations should be ruled-out first, by searching for BRAF V600E mutation and/or MLH1 promoter hypermethylation." (PMID 35954394, 2022). "There were seven (7%) tumours with loss of MLH1 and PMS2 proteins, and these tumours also had high microsatellite instability based on microsatellite instability testing." (PMID 33737597, 2021). "This genomic profile is characteristic of mismatch repair (MMR) deficiency, and NEC-02002 organoids as well as the original tumor indeed showed loss of expression of the MMR proteins PMS2 and MLH1." (PMID 33776923, 2021). "Mice defective in PMS2 endonuclease activity showed significant increase in genomic mutations and tumor incidence." (PMID 34489406, 2021).
tumor (continued). "In agreement, a pan-cancer analysis of MSI found that 78.4% (29/37) of LS-associated microsatellite stable tumours were from carriers of either MSH6 or PMS2 pathogenic variants." (PMID 33499123, 2021). "We found the MLH1 c.1989 + 5G>A variant, which led to aberrant splicing and loss of MLH1 and PMS2 protein in the nuclei of tumour cells." (PMID 34925852, 2021). "One PMS2 positive tumor mutation was proven to be of germline origin, and thus it was considered eligible for immunotherapy treatment." (PMID 33853586, 2021). "The convincing loss of immunodetectability of MSH1 und PMS2 in deeper invasive tumor parts with increased intratumoral immunocytes suggested a MSI phenotype." (PMID 34885191, 2021). "Immunohistochemical analyses for mismatch repair (MMR) proteins revealed the loss of MLH1 as well as PMS2 in cancerous nuclei, which makes the tumor MMR deficient." (PMID 33654584, 2021). "Since the most common molecular event leading to MMRD is MLH1 promoter hypermetylation, the most common immunohistochemical pattern observed in MMRD tumours is MLH1/PMS2 loss." (PMID 32664968, 2020). "The most affected marker was ARID1A, whereby 47% of the cases had a loss of staining in tumor cells as well as stromal tissue and lymphocytes, which are the internal controls, followed by PMS2 (12%), and BRG1 (14%)." (PMID 32677969, 2020). "In one case (CABR46), several arguments pointed towards the presence of a “WES-invisible” second hit mechanism involving the germline PMS2 variant (e.g., gene promoter methylation) leading to a hypermutated tumor." (PMID 32295625, 2020). "One patient demonstrated loss of PMS2 protein in his tumor and harbored a pathogenic variant in exon 12 in PMS2 that was detected by a clinical lab." (PMID 30809968, 2019). "Further, next-generation sequencing (NGS) analysis was performed, and results revealed two tumour-related gene mutations (deletion of PMS2 and variation of ESR1 [L536P])." (PMID 31391089, 2019). "To test for loss of protein product, we stained MLH1, MSH6, and PMS2 in tumour tissue from paraffin blocks, collected from the carriers of the coding variants." (PMID 30324682, 2018). "There was a significantly higher frequency of somatic mutations in DNA mismatch repair genes in Asian tumours, in particular PMS2 (p=0.0036)." (PMID 29682207, 2018). "We found five point mutations in the exon region of PMS2 gene in the DNA samples from paraffin-embedded tumor specimens." (PMID 28347324, 2017).
tumor (continued). "Patient sLS-117 presented with solitary PMS2 protein deficiency in the tumor and only PMS2 had been previously screened with conventional mutation screening." (PMID 27300758, 2016). "In the PMS2 promoter region, one sample had a large increase in methylation across 5 promoter-associated probes when compared with the remaining tumor-derived (Δβ ~14.66%) and blood-derived DNA samples (Δβ 15.44%)." (PMID 27902704, 2016). "Four relapsed tumours were hypermutable with 156–740 coding mutations, two of which had loss-of-function mutations in the DNA mismatch repair genes PMS2 and MSH6 at relapse." (PMID 25790293, 2015). "In malignant prostate cells however, PMS2 levels were found to be less than that observed in normal adjacent areas and in fact, more tumor foci showed loss of PMS2 compared to other MMR genes." (PMID 26036629, 2015). "Comparing APE1, PTEN, NBN, and PMS2 expression in grade 2, 3 and 4 tumours only PTEN expression was associated grade, with increasing grade being associated with increasing levels of PTEN expression (p=0.004)." (PMID 25026297, 2014). "Several studies have demonstrated that PMS2 mutation carriers can be identified among patients with MSI-high tumours and/or loss of PMS2 in tumour tissue." (PMID 24790682, 2014). "In a previous study, we demonstrated that GSK3β inactivation is associated with tumour stage of NPC through regulation of PMS2." (PMID 23874688, 2013). "Of these 16 cases, no cause was determined for 10, but 6 were found to have a heterozygous germline mutation in Pms2, followed by likely loss of heterozygosity in the tumor." (PMID 22494821, 2012). "Her CRC specimen showed loss of expression of PMS2 in tumor cells and in normal colonic surrounding tissue, leading to a presumptive diagnosis of constitutional MMR-deficiency syndrome due to bi-allelic PMS2 mutations." (PMID 23049789, 2012). "In contrast, germline mutations in MSH6 or PMS2 cause isolated loss of the encoded protein in the tumor tissue." (PMID 22547953, 2011). "Because the combination of Mlh3, Pms2 and Apc mutations accelerates tumor progression, we searched MPA GI tumor specific genetic changes associated with progression using high-resolution aCGH." (PMID 18551179, 2008). "All tumours exhibited MLH1/PMS2-deficiency and MLH1 methylation testing of the EC was positive." (PMID 40208414, 2025). "In addition to the ECM-driven mechanisms, the reduced expression of minichromosome maintenance (MCM) proteins observed in the MLH1/PMS2-deficient tumor area underscores a critical aspect of genomic instability." (PMID 40076915, 2025). "Univariate logistic regression analysis revealed that high F. nucleatum abundance (HR=1.967, 95% CI: 1.046-3.698, p=0.036), BRAFV600E mutation (HR=7.368, 95% CI: 2.741-19.809, p<0.001), and tumor size > 5 cm (HR=2.557, 95% CI: 1.362-4.802, p=0.003) were risk factors for PMS2 deficiency." (PMID 40458404, 2025). "Additionally, the loss of PMS2 expression was associated with female sex (p = 0.015), right-sided tumor location (p = 0.003), and poor differentiation (p < 0.001)." (PMID 40941629, 2025).